IL6 (interleukin 6)
Diseases named in the same sentence as IL6 in open-access papers (continued):
Sharing a sentence is not in itself a finding about the gene and the disease.
cancer (continued). "The inflammatory cytokine IL-6 is implicated in the pathogenesis and progression of many human cancers, through the activation of several signal transduction pathways, including JAK/STAT3, RAS/ERK and PI3K/AKT signaling cascades." (PMID 29707128, 2018). "In conclusion, our findings underscore the notion that IL-6 promoter polymorphisms were significantly associated with the susceptibility and prognosis of cancer." (PMID 29552316, 2018). "Lippitz and Harris published a review and reported the serum level of IL-6 was significantly associated with survival in 85.6% of cancer patients (9917/11,583) in 23 different types of cancer." (PMID 28548958, 2017). "Inflammation is additionally linked to cancer development, and increased levels of TNF-α, IL-6, selectins, and leptin and decreased levels of adiponectin are associated with enhanced metastasis and increased risk of several cancers." (PMID 28185008, 2017). "IL-6 is a pleiotropic cytokine implicated as a critical regulator of inflammation-induced skeletal muscle and fat wasting during cancer cachexia." (PMID 28785374, 2017). "Platelet can be activated by inflammatory factors such as interleukin-6, and elevated platelet in peripheral blood is associated to the development of many cancers." (PMID 29262773, 2017). "Strikingly, many SASP factors are known to stimulate phenotypes associated with aggressive cancer cells, such as IL-6 and VEGF." (PMID 28881615, 2017). "Although the IL-6-174G>C polymorphism has been assessed in association with survival of several types of cancer, the results are still inconsistent." (PMID 28548958, 2017). "IL-6 was clearly identified as a key cytokine implicated in cancers of prostatic tissue, breast tissue, and colorectal tissues." (PMID 28356100, 2017). "Cytokines such as tumor necrosis factor-α, interleukin-1, IL-6, and IL-18; oxygen free radicals; and nitrogen-based biological effectors have all been implicated in promoting cancer cell growth." (PMID 28284210, 2017). "Published studies suggest that evaluated expression of IL-6 is associated with cancer risk at the time of diagnosis." (PMID 28548958, 2017). "Previous meta-analysis demonstrated significant association between rs1800796 of IL6 and cancer risk, with the allele G as a risk allele." (PMID 29069743, 2017). "Elevated serum levels of IL-6 have been associated with key features of malignancy, cancer progression, and a poor clinical outcome in different types of cancers." (PMID 28545495, 2017). "Apart from its involvement in LN, IL-6 gene polymorphism also conveys the susceptibility to cancer, lipid metabolic abnormalities, and inflammatory disorders." (PMID 28484449, 2017). "Accumulating evidence has suggested IL-6-174G>C is associated with susceptibility to many types of cancer." (PMID 28548958, 2017). "One of the major M2 TAM-secreted oncogenic cytokines, IL-6, has been implicated in contributing metastatic potential and therapeutic interventions in different cancer types including colon." (PMID 28241877, 2017). "The second pathway has been found to be implicated in most of the deleterious effects of IL-6 in chronic inflammatory diseases and cancer." (PMID 28927416, 2017). "Although previous investigations have confirmed that IL-6 is important in both physiological and pathological angiogenesis, IL-6 has recently received more attention as a critical cytokine implicated in the angiogenesis of several human cancers." (PMID 27903982, 2017). "Because it's difficult to obtain data, there are few studies about IL-6 polymorphism and cancer prognosis." (PMID 28548958, 2017). "Several of these cytokines, including TNF-α, IL-1, and IL-6, have themselves been shown to have an association with worse prognosis in patients with cancer." (PMID 28239396, 2017).
cancer (continued). "During their interaction with cancer cells, adipocytes acquire phenotypic changes (e.g. de-lipidation, de-differentiation) and functional alterations (e.g. increased production of interleukin-6), and are thus referred to as cancer-associated adipocytes." (PMID 28989976, 2017). "Whereas, in various inflammation and autoimmune diseases, as well as inflammation-associated cancer, IL-6 trans-signaling is pro-inflammatory and blockade of it is sufficient to alleviate the inflammatory reaction." (PMID 28484449, 2017). "In other studies in patients with cancer, associations have been shown between appetite loss and IL-1β, IL-6 and IL-8 and with gene polymorphisms coding for TNF-α, IL-1β, and IL-10." (PMID 28542626, 2017). "Elevated serum IL-6 levels and increased activation of the IL-6 signaling pathway, have been observed in many human malignancies, and are associated with cancer initiation and progression." (PMID 28208810, 2017). "Platelet can be activated by inflammatory factors such as interleukin 6, and elevated platelet count in peripheral blood is associated to the onset and progress of many cancers." (PMID 27852044, 2017). "Elevation in IL-6 expression and loss of E-cadherin have been linked with increase cancer stem cell population in various cancer types." (PMID 28077171, 2017). "In this study, we evaluated the association the IL-6-174G>C polymorphism and overall survival (OS) of cancer using 17 eligible studies with 4,304 patients." (PMID 28548958, 2017). "In the present study, we performed the first comprehensive meta-analysis of available studies to obtain a comprehensive evaluation of the association between IL-6-174 polymorphism and cancer prognosis." (PMID 28548958, 2017). "Together, either IL-6 exposure or continuous lenalidomide treatment enhanced A-to-I editing of GLI1 as well as other cancer-associated associated transcripts, including APOBEC3D, AZIN1, and MDM2." (PMID 29203771, 2017). "There is crosstalk between the two pathways in EMT progression, as EGF treatment enhances IL-6 production, and elevated level of IL-6 is associated with cancer cell aggressiveness and metastasis by inducing EMT through activating STAT3 and Akt signaling." (PMID 28903339, 2017). "Aberrantly, elevated IL-6 and IL-6 mRNA levels were observed in the serum of cancer patients and have been associated with poor clinical outcomes." (PMID 28927416, 2017). "Higher levels of serum IL-6 are associated with aggressive cancer and response to therapies in series malignant tumors." (PMID 29296206, 2017). "Schubert and coworkers found cancer related fatigue to be associated with elevated levels of biomarkers IL-6, IL-1 receptor antagonist (IL-1ra) and neopterin." (PMID 28542626, 2017). "Serum IL-6 levels have been reported to be associated with a poor prognosis and treatment failure in patient with many different carcinomas." (PMID 29296206, 2017). "Mouse models, such as the ApcMin/+ [ApcMIN] mutant mouse of intestinal polyposis, have been utilized to study cancer-associated cachexia due to uncontrolled levels of Interleukin (IL)-6 and other host inflammatory responses." (PMID 26933816, 2016). "Increased expression of IL-6 has been reported in different types of cancers and high serum levels of IL-6 have been associated with metastasis and unfavourable prognosis." (PMID 27034885, 2016). "Siltuximab was further studied for its beneficial anti-IL-6 effects in other malignancies, like multiple myeloma, myelodysplastic syndrome, prostate cancer, ovarian cancer and lung cancer, and cancer-associated cachexia and anorexia." (PMID 28083070, 2016). "The -174 G>C (rs1800795) SNP in IL6 has been associated with cancer and cardiovascular disease, nevertheless this association is still controversial." (PMID 27662210, 2016). "Owing to its association with poor prognosis, researchers have proposed IL-6 as a therapeutic target in cancer." (PMID 26989335, 2016).
cancer (continued). "IL-6 is also associated with recruitment of myeloid cells and increased cancer cell growth and migration." (PMID 27283985, 2016). "Such events are linked with the overexpression of SOCS3 that inhibits IL-6 signaling, a key factor in many cancers." (PMID 27190500, 2016). "Blood biomarkers, such as neutrophil count, monocyte count, platelet count, serum C-reactive protein level, serum albumin level, and interleukin-6 level, for the systemic inflammatory response are associated with cancer prognosis." (PMID 27732629, 2016). "Interleukin-6 (IL-6), an important pro-inflammatory cytokine, is found to be associated with many types of cancers." (PMID 27756247, 2016). "IL-6's overexpression, dysregulation, and elevated serum levels have been proven to be associated with many types of cancers, such as multiple myeloma, lung cancer, ovarian cancer, breast cancer, and head and neck cancer." (PMID 27174914, 2016). "Of those, high level of IL-6 in the serum and ascites of the cancer patients has been shown to be associated with worse clinical outcomes." (PMID 27825119, 2016). "Circulating IL-6 levels have been closely associated with weight loss and reduced survival in cancer patients." (PMID 27064118, 2016). "ELISAs revealed MSC-CM contained higher levels of IL-6 and IL-8, which are associated with the progression of cancer." (PMID 26892992, 2016). "Increased level of IL-6 was observed in prostatospheres compared with adherent bulk cancer cells and this was associated with stronger activation of STAT3." (PMID 27732936, 2016). "The cytokine IL-6, as one of the most potent metastatic inducers, is required for the development of inflammation-associated cancers." (PMID 27769047, 2016). "Il-6 is produced by macrophages and is known to be associated with tumorigenesis, cancer growth, and invasion." (PMID 27091202, 2016). "IL-6 signaling has been implicated in various cancers, as the IL-6 receptor complex is linked to JAK activity targeting STAT3." (PMID 26849807, 2016). "Elevated levels of IL-6, hsCRP and/or D-dimer were predictive of cancer, in particular death due to cancer; high D-dimer levels were linked to cancer mortality more strongly than to CVD." (PMID 27171281, 2016). "In human studies, elevated serum IL-6 levels were quite consistently associated with weight loss and a reduced rate of survival in cancer patients." (PMID 26856534, 2016). "Here we will review emerging concepts and mechanisms that underlie the complex biology of IL-6 in regard to its roles in cancer cachexia and skeletal muscle renewal." (PMID 27330885, 2016). "Lamina propria T cells, macrophages, and cancer-associated fibroblasts (CAFs) can all secrete IL-6 in the CRC stroma." (PMID 27148488, 2016). "Several mechanisms associated with cancer cachexia involve cytokines, such as interleukin 1 (IL-1), IL-6, and tumor necrosis factor-α." (PMID 26985904, 2016). "To date, most published studies of associations between IL-6 SNPs and cancer risk focused on rs1800795 and rs1800796." (PMID 27049718, 2016). "First, chronic inflammation per se is associated with the development of cancer, and, for example, prolonged IL-6 signaling and STAT3 activity is known to be pro-tumorogenic." (PMID 26788120, 2016). "In patient sera of many types of cancers, the IL-6 level is elevated and suggested to be associated with poor clinical outcome." (PMID 26675547, 2016). "IL-6 is a central cytokine that is mainly produced by TME components such as cancer-associated fibroblasts (CAF) and tumor-associated macrophages (TAM) [7." (PMID 27483433, 2016). "DEN-induced inflammation stimulates the overexpression of IL-6, IL-6R, gp130 and other pro-tumorigenic cytokines, which in turn further aggravates inflammatory damage to the liver tissues and causes cancer." (PMID 27080032, 2016). "Studies on human cancer cells have shown that KYN activates the AhR-ARNT associated transcription of IL-6, which induced autocrine activation of IDO1 via STAT3." (PMID 26881062, 2015).
cancer (continued). "In this meta-analysis, risk estimates of IL-6 gene -174G/C variant with cancer were heterozygous between Caucasians and Asians." (PMID 26096712, 2015). "Circulating IL-6 is also well described as predictor of weight loss in human cancer cachexia and it contributes to a pathologic state associated with aging called inflamm-aging." (PMID 26251044, 2015). "Dysregulated expression of IL-6 and its receptor are implicated in the pathogenesis of many diseases, including multiple immunorepressive diseases and cancers." (PMID 25973612, 2015). "Here we show that genetic inactivation of Stat3 or IL-6 signalling in a Pten-deficient PCa mouse model accelerates cancer progression leading to metastasis." (PMID 26198641, 2015). "Among the cytokines linked to inflammation-associated cancer, IL-6 appears to drive oncogenesis via downstream activation of the JAK/STAT3 signaling pathway." (PMID 25789077, 2015). "In this study, we show that loss of IL-6/Stat3 signalling in a Pten-deficient PCa model accelerates cancer progression leading to metastasis." (PMID 26198641, 2015). "Interleukin-6 (IL-6) is a classic pro-inflammatory cytokine associated with a variety of pathological conditions, including cancer." (PMID 26282935, 2015). "Increased IL-6 expression in the cancer cells was significantly associated with poor response to preoperative chemoradiotherapy (*P<0.05, **P<0.01, Chi-squared test Table II)." (PMID 25761055, 2015). "The levels of IL-6 are elevated in advanced cancer, and elevated levels in human serum are associated with an increased risk of cancer." (PMID 26418748, 2015). "Reportedly, an increased expression of IL-6 has been investigated in different types of cancers and high serum levels of IL-6 have been associated with metastasis and unfavorable prognosis." (PMID 25761055, 2015). "In the present study, we examined the association of IL-6 expression in cancer cells with clinicopathological factors in the OSCC patients by immunostaining." (PMID 25761055, 2015). "STAT3, in particular, is linked closely with cancer development via activation of immunomodulatory cytokines (IL-6, IL-10, and IL-17), growth factors (FGF, VEGF), and matrix metalloproteinases." (PMID 26538823, 2015). "It is also worth noting that IL-6 gene -174G/C variant exhibited heterozygous association with different forms of cancer in this meta-analysis." (PMID 26096712, 2015). "In the present study, we found on a subset of samples where RNA were available, that the CC variant of rs2853669 is associated with an increased expression of IL-6 and TNFα, cytokines considered as markers for inflammation and cancer progression." (PMID 26298771, 2015). "The proinflammatory cytokines, including TNF-α, IL-6, and IL-1β have been regarded as crucial factors causing cancer cachexia and muscle atrophy." (PMID 26600425, 2015). "It has been reported that cancers associated with inflammatory cytokines including interleukin-6 are associated with deterioration of patient PS." (PMID 26460792, 2015). "For instance, IL-6 >2.19 pg/mL was associated with an increased risk of all-cause mortality (cardiovascular diseases, cancers and other causes) among older adults across a 9-year period." (PMID 26378783, 2015). "It is particularly interesting that studies of pain in cancer patients have shown the importance of cytokine genes including IL6, TNF and IL1B polymorphisms." (PMID 26269716, 2015). "Several observational studies have suggested that circulating IL-6 can explain inter-individual variability in predisposition to cancer." (PMID 26096712, 2015). "For instance, the paracrine sources of IL-6 from cancer-associated fibroblasts, adipocytes, or myeloid cells on the edge of the tumors and the autocrine production of IL-6 can both activate the STAT3." (PMID 26631279, 2015). "IL-6 has been linked to the upregulation of proteases such as cysteine cathepsins and matrix metalloproteinases that are known to play a role in cancer progression." (PMID 26268945, 2015).
cancer (continued). "The frequency of IL-6 gene -174C allele ranged from 0.0% to 52.94% in cancer patients and from 0.0% to 51.15% in healthy controls." (PMID 26096712, 2015). "Given the insufficient statistical power of this meta-analysis in some subgroups, far larger sample sizes than studied here will be required to produce enough power to evaluate the causality between circulating IL-6 and various forms of cancer." (PMID 26096712, 2015). "As a multifunctional cytokine, IL-6 has been implicated in the maintenance of stem cancer cells through the IL-6/gp130/STAT3 signaling pathway." (PMID 26631279, 2015). "Multiple cytokines have been documented to promote weight loss during either cancer or chronic infections including IL-1, IL-6, IFN-γ and TNF-α." (PMID 25769044, 2015). "In cancer, fatigue has been closely associated with depressed mood and increased levels of IL-6, a cytokine observed within MPNs." (PMID 26538823, 2015). "The results showed that increased IL-6 expression in the cancer cells was significantly associated with poor response to preoperative chemoradiotherapy." (PMID 25761055, 2015). "Seventy-eight and six articles were eligible for the association of -174G/C variant with cancer and circulating IL-6, respectively." (PMID 26096712, 2015). "An important mediator implicated in the development of cancer cachexia is the transcription factor STAT3 that previous work has shown activated by circulating pro-inflammatory cytokines (i.e. IL-6)." (PMID 25460504, 2015). "Adipose atrophy has been associated with elevated IL-6 signalling in a preclinical model of cancer cachexia." (PMID 26508820, 2015). "S1PR1, one of the common targets of miR-148a-3p, -148b-3p and -363-3p, is implicated in NFκB/IL-6/STAT3/S1PR1 amplification loop that is important for chronic colitis-related cancer and can be suggested as therapeutic option." (PMID 26692821, 2015). "Many factors have been implicated in cancer cachexia including cytokines (TNFα, IL-6), ZAG and myostatin." (PMID 24667661, 2014). "As a pleiotropic cytokine, IL-6 is associated with the development and progression of multiple types of cancer." (PMID 25419563, 2014). "Interleukin-6 (IL-6) is a multifunctional cytokine associated with disease status and cancer outcomes." (PMID 24398980, 2014). "Pro-inflammatory cytokines, such as TNF-α, IL-1, and IL-6, have been implicated in the development of cancer cachexia and have been shown to exhibit synergistic effects." (PMID 24624094, 2014). "By contrast, different pathologic conditions promoting muscle wasting, including cancer, are associated with elevated systemic levels of IL-6." (PMID 24967341, 2014). "IL-6 level was the only factor other than disease stage that independently predicted Hb levels in cancer associated ACD." (PMID 24878740, 2014). "The importance of the IL-6/STAT3 axis has been linked to supporting CSC populations in a variety of cancers, including hepatocellular, breast, head and neck cancers and glioblastoma." (PMID 24722453, 2014). "IL-6, in turn, is upregulated in various tumors and has been implicated in the capacity of cancer cells to metastasize to bone." (PMID 24901008, 2014). "IL-6 is a critical cytokine secreted in several cancer types, and circulating levels of this cytokine have been shown to correlate with weight loss in cancer patients and reduced survival." (PMID 25436606, 2014). "In previous reports a direct causal link between cancer and inflammation has been described with IL6, let-7, Lin28, and NFκB being the major players involved in the epigenetic switch from inflammation to cell transformation." (PMID 25276782, 2014). "The IL-6 was elevated before the treatment in many of these advanced cancer patients, the changes associated with zoledronate and/or Vγ9Vδ2 T-cells were not clear." (PMID 24515916, 2014). "IL-6 and IL-23 have been shown to be involved in immuno-editing in carcinoma microenvironments and is associated with poor prognosis." (PMID 24842612, 2014).